GLI3 (GLI family zinc finger 3)
Diseases named in the same sentence as GLI3 in open-access papers (continued):
Sharing a sentence is not in itself a finding about the gene and the disease.
ciliopathies (9 papers, 2015 to 2025). "It is considered a ciliopathy, as it is associated with loss-of-function variants in the GLI3 gene, a transcription factor essential for primary cilium signaling." (PMID 41063613, 2025). "So, Shh–Gli3 signaling pathway is affected with most of the ciliopathies with PAP association and that may be due to altered Gli3R/Gli3A ratio." (PMID 25717468, 2015). "The TMEM216-SUFU-GLI2/GLI3 axis plays an essential role in ciliopathies and aberrant Hedgehog (Hh) signaling induced by TMEM216 deficiency." (PMID 40365501, 2025). "Moreover, laryngeal stenosis or narrowing is observed in ciliopathies, consistent with glottic narrowing in Gli3 mutants." (PMID 28177282, 2017). "Besides PAP, there were few cases reported overlapping in their clinical features with Gli3 and ciliopathies." (PMID 25717468, 2015). "Genes related to Shh–Gli3 pathway was the commonest group in non-ciliopathies." (PMID 25717468, 2015). "Interestingly, diencephalic hamartomas have been linked to mutations in GLI3 and other SHH pathway genes, suggesting that those observed in ciliopathies could also be caused by defects in SHH signaling." (PMID 30692221, 2019).
craniosynostosis (9 papers, 2017 to 2024). Craniosynostosis is defined as the premature fusion of one or more cranial sutures leading to secondary distortion of skull shape resulting in skull deformities with a variable presentation. "The deletion of Gli3 results in an increased ossification of calvarial bone, causing craniosynostosis." (PMID 35173529, 2022). "Mutations in other HH pathway members such as Ptch1, Smo, Gli3, and Rab23 also cause craniosynostosis in humans and/or mice." (PMID 34880220, 2021). "GLI3 loss of function mutations cause craniosynostosis resulting in fusion across the interfrontal suture in patients and across the lambdoid and interfrontal sutures in mice." (PMID 29311969, 2017). "Notably, a part of these clinical features, such as craniosynostosis, hypertelorism and syndactyly, are also reported in patients with GLI3 variants." (PMID 38020913, 2023). "Previous studies reported that Gli3 null mice (Gli3xt/xt) exhibited craniosynostosis, a premature closure of cranial sutures, which frequently results in abnormal shape of skulls." (PMID 38020913, 2023). "The suppression of a repressor of Hh signaling (Gli3) leads to craniosynostosis of the lambdoid suture in mice." (PMID 37443368, 2023). "Two mouse models of craniosynostosis have been reported with abnormal processing of GLI3 as an etiological factor." (PMID 29311969, 2017). "Loss-of-function mutations in GLI3 and IHH cause craniosynostosis and reduced osteogenesis, respectively." (PMID 29311969, 2017). "Even in the absence of Ihh, Gli3 deletion was sufficient to induce aberrant precocious ossification across the developing suture, indicating that the craniosynostosis phenotype of Gli3Xt−J/Xt−J mice is not dependent on IHH ligand." (PMID 29311969, 2017). "This highlights the repressive role of GLI3 and also that craniosynostosis is not just excessive osteogenesis but a patterning defect." (PMID 29311969, 2017). "We have shown earlier how Gli3Xt−J/Xt−J mice, which produce no functional GLI3 protein, can be used as a model to study craniosynostosis and suture biogenesis, and by genetically reducing the dosage of Runx2 the calvarial phenotype can be rescued." (PMID 29311969, 2017). "We also demonstrate a location specific regulatory role for GLI3 repressor within the suture which is independent of IHH expression, as Ihh deletion does not rescue craniosynostosis exhibited by Gli3Xt−J/Xt−J mice." (PMID 29311969, 2017).
liver fibrosis (9 papers, 2012 to 2021). "Both miR-152 and miR-378a-3p have been shown to negatively regulate GLI3 in liver fibrosis in vitro and in vivo." (PMID 32245491, 2020). "In the current study, the Hh-related genes, including Bmp4, Gas1, Gli3, Hhip, Ihh, Prkacb, Stk36, Wnt6, Wnt10b, Wnt9a and Wnt11, were dysregulated in our murine model of CCl4-induced liver fibrosis." (PMID 27322257, 2016). "Our results demonstrate that miR-378a-3p suppresses activation of HSCs by targeting Gli3 and its expression is regulated by Smo-dependent NF-κB signalling, suggesting miR-378a-3p has therapeutic potential for liver fibrosis." (PMID 27001906, 2016). "Moreover, miR-125b, miR-378, and miR-152 can prevent liver fibrosis by regulating the expression of GLI family zinc finger 3 (Gli3)." (PMID 34360904, 2021). "MiR-378-3p could also limit the activation of hepatic stellate cells and liver fibrosis by suppressing the expression of Gli3." (PMID 34795209, 2021). "In addition to early reports of the role of GLI3 in the development of the brain, lungs, sperm and in genetic diseases, the biological significance of GLI3 was also suggested in diseases such as liver fibrosis, cancer, and in the immune system." (PMID 32245491, 2020). "miR-378a-3p could suppresses activation of hepatic stellate cells by targeting Gli3 and its expression is regulated by Smo-dependent NF-ΚB signaling, suggesting miR-378a-3p has therapeutic potential for liver fibrosis." (PMID 29088758, 2017). "In addition to their role in tumorigenesis, micro RNAs appear to regulate GLI3 in liver fibrosis." (PMID 32245491, 2020). "Using rodent models of liver fibrosis where fibrosis was chemically induced with CCI4 in mice, GLI3 expression was increased (miR378a-3p downregulated) in tissue isolated from animals suffering from liver fibrosis suggesting GLI3 positively regulates liver fibrosis." (PMID 32245491, 2020).
hypospadias (8 papers, 2019 to 2025). Hypospadias is the displacement of the urethral meatus on the ventrum of the penis. "We found that Gli3XtJ mutant mice exhibit cryptorchidism and hypospadias due to local effects of GLI3 loss and systemic effects of testicular hormone deficiency." (PMID 32497091, 2020). "Among the eighteen genes, four have been previously identified in patients with hypospadias (CYP1A1, FLNA, GLI3, and GLI2), three have been reported to be associated with cryptorchidism (FLNA, RET, and PTPN11), and one has been identified in patients with micropenis (EVC)." (PMID 33424767, 2020). "Androgen supplementation partially rescued testicular descent but not hypospadias in Gli3XtJ mutants, decoupling local effects of GLI3 loss from systemic effects of androgen insufficiency." (PMID 32497091, 2020).
medulloblastoma (8 papers, 2017 to 2023). A malignant, invasive embryonal neoplasm arising from the cerebellum. "Another point to raise in this context is that Atoh1, Gli3, and Mycn are all up-regulated in a subtype of medulloblastoma that originates from GCs." (PMID 37491148, 2023). "In contrast, primary cilia of medulloblastoma and basal cell skin carcinoma caused by gain-of-function mutation of GLI2 increases the activity of GLI3 as a transcriptional repressor, resulting in suppression of the proliferation of these cancer cells." (PMID 32825105, 2020). "GLI3 was highly expressed in medulloblastoma cell line D283 compared to RD-ES (p < 0.01)." (PMID 33924679, 2021). "This suggests a role for GLI3 as a prognostically favorable factor in medulloblastoma." (PMID 32245491, 2020). "A role for GLI3 as a tumor suppressor was reported in medulloblastoma and AML." (PMID 32245491, 2020). "GLI2 and GLI3 are two of the principle mediators of the sonic hedgehog signaling pathway (Shh) and are upregulated in SHH-medulloblastomas (SHH-MB) relative to normal brain samples." (PMID 29099739, 2017). "Furthermore, analysis of patient samples revealed an enrichment of several hedgehog pathway genes, such as GLI2, GLI3 and HHIP in cells from medulloblastoma patients expressing high SCARB1 levels." (PMID 29352211, 2018). "In this brief report, following an analysis of microarrays of medulloblastoma patients, we identify key proteins—such as LSD1, EZH2, GLI2, GLI3, and PTK7—that may serve as drug targets." (PMID 29099739, 2017). "GLI3 was found to be present in 94% of neuronal differentiation and glial and neuronal differentiation medulloblastoma, while it could not be detected in any of the differentiation-free medulloblastoma." (PMID 32245491, 2020). "SHH mediators GLI2 and GLI3 are significantly upregulated in SHH-MB, but GLI3 is not upregulated in the larger pool of medulloblastomas, and there is only weak evidence that GLI2 is upregulated." (PMID 29099739, 2017).
pancreatic cancer (8 papers, 2020 to 2023). "A recent work by Ma and collaborators demonstrated that GLI3 is significantly correlated with distant metastasis, vascular invasion, and histologic grade in pancreatic cancer patients." (PMID 33266496, 2020). "Since cyclopmine’s reduction of cell viability is due to the initiation of pro-apoptotic cell machinery, the question arises as to what degree GLI3 is involved in regulating the apoptotic pathway in pancreatic cancer cells." (PMID 32245491, 2020). "Notably, the GLI family of HH transcription factors (GLI1, GLI2, GLI3), remain largely unexplored in pancreatic cancer." (PMID 35867772, 2022). "However, GLI3-FL has been reported to directly interact with the androgen receptor and stimulation of pancreatic cancer cells with the synthetic androgen “R1881” (methyltrienolone) leads to the nuclear translocation of GLI3-FL and subsequent promoter activation of specific GLI consensus sequences." (PMID 32245491, 2020). "We demonstrate that IPMNs and MCNs are precursors of invasive pancreatic cancer, that alterations in ATM, GLI3, and SF3B1 are present in these lesions, and that SMAD4/TGFBR2 alterations are likely drivers of invasion in a subset of cases." (PMID 32796935, 2020). "In pancreatic cancer cells such as PANC-1, targeting GLI3 with siRNA reduced cell viability." (PMID 32245491, 2020). "As opposite to GLI3, the transmembrane protein MEGF8, which interacts with mahogunin ring finger-1 (MGRN1) for the ubiquitination and degradation of Smo, is not correlated with pancreatic cancer." (PMID 33266496, 2020).
prostate carcinoma (8 papers, 2013 to 2025). A carcinoma that arises from epithelial cells of the prostate gland. "The link between SPOP mutations and the stabilization of GLI3 provides insights into the genetic basis of prostate cancer." (PMID 40432836, 2025). "In a more recent study, GLI3-FL was suggested to be involved in the induction of castration-resistant prostate cancer (GRPC) through a mutated form of MED12 which is common in prostate cancer." (PMID 32245491, 2020). "The study suggests that factors regulating GLI3 expression and activity could significantly impact the development and progression of prostate cancer, particularly in the context of SPOP mutations." (PMID 40432836, 2025). "GLI3 is found to be expressed at significantly higher levels in prostate cancer cell lines, tumor xenografts, and human prostate tumor tissues." (PMID 40432836, 2025). "Targeted depletion of GLI3 in prostate cancer cells prevents the acquisition of androgen-independent growth." (PMID 40432836, 2025). "When androgens are withdrawn, GLI3 levels increase in prostate cancer cells, contributing to the development of androgen-independent growth." (PMID 40432836, 2025). "Mutations in the SPOP gene, which are frequently found in primary prostate cancer, stabilize GLI3, leading to its pathologic accumulation." (PMID 40432836, 2025). "E3 ubiquitin ligase adaptor protein SPOP targets GLI3 for ubiquitin-mediated proteasomal degradation in prostate cancer cells." (PMID 40432836, 2025). "Dysregulated GLI3-dependent SHH signaling, as a result of mutant or downregulated MED12, has been shown to play an important role in X-linked disability syndromes and prostate cancer progression." (PMID 38915457, 2024). "Targeting GLI3 may help address this resistance and develop more effective treatments for advanced prostate cancer." (PMID 40432836, 2025). "Excessive activation of GLI3 promotes prostate cancer growth." (PMID 38498906, 2024). "Therefore, in this study, we have investigated the link between MED12 and GLI3-dependent SHH signaling and how MED12 mutations promote progression of primary prostate cancer towards CRPC." (PMID 37520466, 2023). "GLI3 and AR appear to cooperate in promoting androgen-independent growth in SPOP-mutant prostate cancer cells." (PMID 40432836, 2025). "Since a common therapy for prostate cancer is androgen depletion, and in the presence of mutated MED12 SHH induced GLI3 gene expression is activated when androgen is absent, new or additional therapeutic approaches might be necessary to reduce the risk of prostate cancer relapse." (PMID 32245491, 2020). "Furthermore, the question remains whether there is a direct interaction between GLI3 and MED12 in prostate cancer." (PMID 32245491, 2020).
glioma (7 papers, 2010 to 2025). A benign or malignant brain and spinal cord tumor that arises from glial cells (astrocytes, oligodendrocytes, ependymal cells). "Some of the genes defined as REST-activated targets (i.e. NTF3 and GLI3) containing KAISO motifs within the REST ChIP-seq peaks had a methylation pattern similar to the repressed REST targets across glioma tumor types." (PMID 38711090, 2024). "The incubation of glioma cells with siRNA against GLI1, GLI2, or GLI3 resulted in death of glioma cells." (PMID 30730955, 2019). "According these data, in glioma cells, gli3 acted more as an activator, than repressor of transcription." (PMID 30730955, 2019). "We performed Western-blotting of gli1 and gli3 proteins for four primary glioma cell lines, but the data were unexpected." (PMID 30730955, 2019). "Gli1, the founding member, was initially identified as being highly amplified in gliomas, and Gli2 and Gli3 were subsequently cloned by hybridization." (PMID 20865152, 2010). "However, GLI3 knockdown showed that gli3 acted in glioma cells more as an activator, than a repressor of transcription, despite the high level of Gli3R." (PMID 30730955, 2019). "Treatment with GANT61 or siRNA against GLI1, GLI2, or GLI3 could result in complete glioma cell death, while cyclopamine had a weaker and line-specific effect on glioma cell survival." (PMID 30730955, 2019). "The expression of GLI1, GLI2, GLI3 and their target genes FOXM1 and BMI1 was analyzed by RT-qPCR for 20 glioma cell lines and a normal adult brain tissue." (PMID 30730955, 2019). "According to our data, treatment of glioma cells with GANT61 or siRNA against GLI1, GLI2, or GLI3 resulted in their death, indicating, that gli contribute to glioma cells survival." (PMID 30730955, 2019). "The treatment of glioma cells with cyclopamine, GANT61 or siRNA against GLI1, GLI2, or GLI3 significantly decreased the expression of GLI1, FOXM1, BMI1, SOX2, and OCT4, involving in the maintenance of the stem cell state." (PMID 30730955, 2019). "Since the 1987 discovery of GLI1 in human glioma cells, the role of the three members GLI1, GLI2 and GLI3 in a variety of cancers has become increasingly apparent, with GLI1 expression specifically identified as a negative prognostic factor in numerous cancers." (PMID 34639011, 2021). "Thus, the expression of the components of the Shh signaling pathway, including GLI1, GLI2, GLI3, PTCH, and SMO, was found to be common in various tumors of the nervous system, including gliomas, and correlated with a poor prognosis of patient survival." (PMID 30730955, 2019).
cryptorchidism (6 papers, 2011 to 2025). The failure of one or both testes of a male fetus to descend from the abdomen into the scrotum during the late part of pregnancy. "Reviewing previously reported GLI3 mutation subjects with GCPS or oral-facial-digital syndrome indicates that a small minority of these patients also display micropenis, cryptorchidism, or anosmia." (PMID 31767679, 2020).
hypothalamic hamartoma (6 papers, 2018 to 2024). "Here, we describe the identification of a novel nonsense GLI3 pathogenic variant in an adult male following the incidental detection of a hypothalamic hamartoma." (PMID 30455963, 2018). "This suppressor activity of mutated GLI3 might be related to hypothalamic hamartoma formation, however further studies are necessary to confirm the role of GLI3-R and HH signaling in this tumor development." (PMID 32245491, 2020). "However patients suffering from PHS also have a high recurrence of hypothalamic hamartoma, suggesting a role of GLI3 in regulating benign brain tumor formation." (PMID 32245491, 2020).
melanoma (6 papers, 2017 to 2026). A malignant, usually aggressive tumor composed of atypical, neoplastic melanocytes. "Other downstream counterparts of Hh signaling pathway such as Gli-2 and Gli-3 have been associated with melanoma as well." (PMID 28212537, 2017). "We applied RNA sequencing and combined it with ChIP sequencing to identify direct but also unique and overlapping targets of GLI1, GLI2, and GLI3 in three melanoma cell lines." (PMID 36139698, 2022). "qPCR results show that SPRY2 is detected in all melanoma cell lines, especially those with GLI3 overexpression." (PMID 36139698, 2022). "We find that itraconazole increases Gli-3, Axin-1 expression but decreases Gli-1, Gli-2, Axin-1, β-catenin, Wnt3A and Cyclin D1 expression in both melanoma cell lines when compared with untreated cells." (PMID 28212537, 2017). "Notably, cells derived from advanced metastatic lesions exhibited a more pronounced phenotype, characterized by significantly lower levels of three key repressor proteins, PTCH1, SUFU, and GLI3, compared to primary melanoma cells." (PMID 41596411, 2026). "Inhibition of the Hh pathway seems to be a promising target in melanoma; it is reported that an elevated SMO expression is associated with a shorter survival of melanoma patients, while higher GLI3 (Hh pathway repressor) expression is related to better survival." (PMID 38399442, 2024). "In order to confirm HH-GLI pathway activation in melanoma cell lines, we analyzed relative gene and protein expression levels of the pathway components (GLI1, GLI2, GLI3, and PTCH1) on a panel of 14 human melanoma cell lines with different genetic backgrounds." (PMID 36139698, 2022). "Another interesting finding is that GLI3 shows stronger staining in the basal layer in the epidermis of low-stage melanoma, unlike all other tested proteins." (PMID 38892279, 2024).
gastric cancer (5 papers, 2016 to 2021). A primary or metastatic malignant neoplasm involving the stomach. "GLI3 was mutated in 6.9% of microsatellite-stable gastric cancers: because GLI3 generally functions as a transcriptional repressor, its loss would be expected to lead to a net increase in Gli transcriptional activity." (PMID 26859571, 2016). "GLI3, LAMA1, and LRRK2 are found to be significantly associated with the survival of gastric cancer in subtype C1." (PMID 34728653, 2021). "Since multiple studies report the involvement of SHH in gastric cancer, it is possible that GLI3 is mediating SHH-induced effects." (PMID 32245491, 2020). "However additional studies are needed to confirm the specific regulatory role of GLI3 in gastric cancer development and progression." (PMID 32245491, 2020). "In addition to OSCC cancer stem cells, gastric cancer stem cells, that were sorted based on CD44+ CD24+ surface expression, showed 80-fold higher GLI3 mRNA expression than the CD44lo CD24lo phenotype which positively correlated with mRNA expression of SHH and PTCH1." (PMID 32245491, 2020). "Additionally, given the role of GLI3 in regulating cancer stem cells in OSCC and gastric cancer, it might be useful to determine the role of GLI3 in regulating bladder cancer stem cell characteristics and survival as well." (PMID 32245491, 2020).